FJX1 (four-jointed box kinase 1)
Description:
Acts as an inhibitor of dendrite extension and branching.
Synonyms: FLJ22416; FLJ25593
Tractability: Antibody: UniProt places it where antibodies can reach, with medium confidence; UniProt predicts a signal peptide or a membrane-spanning region; its Gene Ontology location is reachable by antibodies, with medium confidence.
Gene: Protein-coding gene on chromosome 11 (35,618,460 to 35,620,865, forward strand). Ensembl gene ENSG00000179431.
Subcellular location: Secreted
Subcellular location (Human Protein Atlas): Vesicles
Gene Ontology:
Molecular function: protein serine/threonine kinase activity
Biological process: cell-cell signaling
Cellular component: extracellular region
Genetic constraint (gnomAD): Loss-of-function variants: 20 observed, 19.39 expected, observed/expected ratio (o/e) 1.03, 90% interval 0.73 to 1.5. The synonymous counts are far from expectation, so gnomAD's model fits this gene poorly and the ratio says little. Missense variants: 585 observed, 449.07 expected, observed/expected ratio (o/e) 1.3, 90% interval 1.22 to 1.39. Synonymous variants: 300 observed, 211.41 expected, observed/expected ratio (o/e) 1.42, 90% interval 1.29 to 1.56.
Homologues: Orthologues: chimpanzee FJX1 (99% identical), macaque FJX1 (97% identical), rabbit FJX1 (93% identical), pig FJX1 (92% identical), rat Fjx1 (90% identical), mouse Fjx1 (90% identical), guinea pig FJX1 (86% identical), dog FJX1 (85% identical), tropical clawed frog fjx1 (45% identical), zebrafish fjx1 (38% identical), Drosophila melanogaster fj (29% identical).
Diseases named in the same sentence as FJX1 in open-access papers:
FJX1 is named in the same sentence as 37 diseases in open-access papers, as found by Europe PMC text mining. Sharing a sentence is not in itself a finding about the gene and the disease. The quoted sentences say what the papers report.
colorectal cancer (6 papers, 2013 to 2024). A primary or metastatic malignant neoplasm that affects the colon or rectum. "Previous studies have shown that FJX1 is highly expressed in some cancers, and in colorectal carcinoma, upregulated FJX1 is significantly associated with poor survival." (PMID 37324001, 2023). "To correlate our observations linking increased angiogenesis with enhanced FJX1 expression (either in vivo or in vitro) we queried two human colorectal cancer datasets for association between expression of FJX1 and known angiogenesis factors." (PMID 23922772, 2013). "Here, we report evidence that FJX1 is a regulator of angiogenesis and higher levels of FJX1 expression are associated with poor patient prognosis in colorectal cancer." (PMID 23922772, 2013). "These genes, including HIF1-α, VEGF receptors Flt1 and KDR, and VEGFC, suggest an association of FJX1 and angiogenic gene expression in human colorectal cancer tumor samples." (PMID 23922772, 2013). "In conclusion, FJX1 may not only be a cause of colorectal cancer but also a risk factor for liver metastasis as a prognostic biomarker." (PMID 35928453, 2022). "It was reported that the transcription level of FJX1 was inhibited by miR-1249, thereby reducing the cell proliferation, migration, and invasion of colorectal cancer." (PMID 35928453, 2022). "The immunohistochemical staining showed that the expression of FJX1 in colorectal cancer tissues was significantly different from that in normal colon tissues, while the protein level of KLHL35 was not significantly different." (PMID 35928453, 2022). "In conclusion, we provide the first evidence that FJX1 mRNA and protein expression is increased in the epithelial cell compartment of advanced colorectal cancers." (PMID 23922772, 2013). "In order to identify the mechanism by which FJX1 elicits pro-angiogenic activity in tumor cells, we analyzed the top 500 genes that are most highly correlated with FJX1 expression in two human colorectal cancer datasets from VUMC and MCC." (PMID 23922772, 2013). "FJX1 mRNA expression in colorectal cancer tissues is significantly correlated with changes in known angiogenesis genes." (PMID 23922772, 2013). "We identified four jointed box 1 (FJX1) as a candidate regulator of tumor angiogenesis in colorectal cancer." (PMID 23922772, 2013). "Moreover, FJX1 has been shown to promote angiogenesis in colorectal carcinoma and potentiate invasion by regulating planar cell polarity, which is involved in wound repair and development." (PMID 37324001, 2023). "FJX1 may be a critical target in colorectal cancer metastasis, and thus has the potential as a new biomarker to predict and treat colorectal cancer liver metastases." (PMID 35928453, 2022). "FJX1 was the most clinically important colorectal cancer prognostic gene and affects biological pathways such as chromogenic modifying enzymes and Notch signaling, as well as cellular senescence and other signaling pathways, according to a KEGG enrichment study." (PMID 35928453, 2022). "Since FJX1 protein is a secreted molecule, it will be interesting to determine if FJX1 protein levels can be detected in patient blood or urinary samples and serve as a biomarker for colorectal cancers." (PMID 23922772, 2013). "Therefore, FJX1 may be a new target for colorectal cancer liver metastasis." (PMID 35928453, 2022). "By regulating the miR-106b-5p/FJX1 axis, knockdown of PVT1 can impair cell proliferation, migration, and invasion in colorectal cancer." (PMID 34336125, 2021). "Next, we examined if FJX1 expression correlated with patient survival in a subset of stage I–III CRC patient samples from the VUMC and MCC colorectal cancer gene expression array datasets (n = 191)." (PMID 23922772, 2013). "In colorectal cancer cells where lncPVT1 is upregulated, it exerts a sponge activity on miR-106b-5p and consequently leading to the aberrant expression of the miRNA target FJX1 (Four jointed box 1) that is involved in cancer progression." (PMID 35090471, 2022).
colon cancer (5 papers, 2013 to 2026). "Additionally, high FJX1 expression has been linked to poor survival in colon cancer and can regulate important proteins in cell cycle progression to enhance proliferation and invasion in nasopharyngeal carcinoma." (PMID 37324001, 2023). "Our external experimental results also demonstrated that knocking down FJX1 in colon cancer cells weakened their proliferation and migration." (PMID 37324001, 2023). "Clinical analysis revealed the highest correlation between FJX1 and clinical factors, nevertheless, FJX1 was more significantly expressed in metastatic liver cancer than in the original colon cancer from GEO." (PMID 35928453, 2022). "There was also a significant difference between FJX1 mRNA expression when stages 1 and 2 were compared to stages 3 and 4 (P<0.02), indicating that FJX1 expression is further increased in more advanced stages of colon cancer." (PMID 23922772, 2013). "Augmented expression of FJX1 in colon cancer cells promotes growth of xenografts in athymic mice and is associated with increased tumor cell proliferation and vascularization." (PMID 23922772, 2013). "When FJX1 was knocked down in colon cancer cells, the expression of TGFB1 and IL-10 also decreased, suggesting that FJX1 may affect the polarization of macrophages and thus the tumor microenvironment." (PMID 37324001, 2023). "Finally, we evaluated the impact of FJX1 on colon cancer cell proliferation and migration through in vitro functional experiments." (PMID 37324001, 2023). "To validate our findings, we performed functional experiments in vitro to determine whether FJX1 promotes colon cancer cell proliferation and migration." (PMID 37324001, 2023). "In colon cancer cells, FJX1 knockdown was found to decrease cell proliferation and migration." (PMID 37324001, 2023). "While its biological function and tumor pathogenesis in human cancer are not fully understood, studies have found that FJX1 is highly expressed in several types of cancer, including head and neck cancer, colon cancer, breast cancer, ovarian cancer, and lung cancer." (PMID 37324001, 2023). "Moreover, we noted that some of the mRNAs (ANLN, CFL2, FJX1, HHIP, PANX2, SCN3A, VSNL1 and ZIC2) were also associated with overall survival in patients with colon cancer." (PMID 29420609, 2018). "To validate our microarray findings, we conducted quantitative RT-PCR analysis for FJX1 mRNA and found FJX1 mRNA expression levels were between five- and seventy-fold higher in colon cancer tissues than in normal adjacent tissue from the same patient (one-sided t-test P<0.0004)." (PMID 23922772, 2013). "FJX1 may promote endothelial cell capillary formation in a hypoxia-inducible factor 1-dependent manner, as well as act as a proto-oncogene that affects metastasis and recurrence in colon cancer patients." (PMID 35928453, 2022). "We therefore engineered a C-terminal MYC-tagged version of human FJX1 and expressed it in human embryonic kidney cells (HEK293T) and colon cancer cells (SW480, KM12C)." (PMID 23922772, 2013). "Although we initially identified a concordant relationship between FJX1 mRNA and HIF1-α mRNA expression in human colonic tumors, we were only able to attribute a post-translational role of FJX1 on HIF1-α regulation in vitro." (PMID 23922772, 2013). "The clinical relevance of CSTL1, FJX1, IER5L, and KLHL35 in 521 colon cancer cases was assessed, showing the expression level of CSTL1 mRNA was higher than that in normal tissues, and the expression levels of PD, SD, PR, and CR were higher than those in normal tissues." (PMID 35928453, 2022). "In order to determine whether endogenous expression of FJX1 has an influence on tumorigenesis, we employed a well-characterized model of inflammation/carcinogenesis using AOM and DSS to induce colonic tumors in mice." (PMID 23922772, 2013).
colon cancer (continued). "Our ability to reliably detect endogenous FJX1 in the epithelial cells of colon tumor specimens, but not in immortalized colon cancer cell lines suggests that expression of FJX1 may require paracrine signaling or matrix interactions not supported through standard cell culture conditions." (PMID 23922772, 2013).
nasopharyngeal carcinoma (5 papers, 2015 to 2023). A carcinoma arising from the nasopharyngeal epithelium. "In summary, we demonstrated that FJX1 confers a survival advantage and invasive potential to nasopharyngeal carcinoma and is a likely target for the treatment of cancer." (PMID 31236144, 2019). "The overexpression of FJX1 is observed at both the mRNA and protein levels in primary nasopharyngeal carcinoma (NPC)." (PMID 36825005, 2023). "The murine equivalent of Fj, four-jointed box 1 (FJX1) is involved in forming appropriate dendrite arbor morphology in the hippocampus, and recently, human FJX1 has been shown to increase the invasive potential of nasopharyngeal cancer cells." (PMID 33759783, 2021).
endometriosis (4 papers, 2019 to 2022). The growth of functional endometrial tissue in anatomic sites outside the uterine body. "The Notch-induced four jointed box 1 (FJX1) protein has also been considered a possible pro-angiogenic factor in endometriosis." (PMID 36304032, 2021). "The authors found significantly higher levels of the FJX1 protein during the secretory phase, which manifest its dependency by the menstrual cycle in endometriosis." (PMID 33435569, 2021). "In eutopic tissue from human and baboon models with endometriosis, FJX1 was significantly increased during the secretory phase." (PMID 36304032, 2021). "The role of FJX1 in endometriosis needs further investigation." (PMID 33435569, 2021). "Increased activation of the Notch signaling pathway in endometriosis could be a reasonable assumption since it induces FJX1 expression." (PMID 36304032, 2021). "FJX1 is also found to be overexpressed in endometrium tissues from women with endometriosis." (PMID 31236144, 2019). "FJX1 has also been identified as an inhibitor of dendrite extension; however, such a role in endometriosis still has not been clarified." (PMID 33435569, 2021). "However, other upstream factors must be dysregulated in endometriosis since FJX1 was not significantly raised in the normal endometrium." (PMID 36304032, 2021).
melanoma (3 papers, 2021 to 2023). A malignant, usually aggressive tumor composed of atypical, neoplastic melanocytes. "lncRNA forkhead box D3 antisense RNA 1 (FOXD3-AS1) is overexpressed in melanoma and functions as oncogene by sponging miR-127-3p and miR-325 and upregulating their target genes four-jointed box kinase 1 (FJX1) and mitogen-activated protein kinase kinase kinase 2 (MAP3K2), respectively." (PMID 34638331, 2021). "Moreover, it was found that FOXD3-AS1 enhanced cell apoptosis of melanoma A375, SK-MEL-1 and SK-MEL-2 cells through either the miR-325/MAP3K2 axis or the miR-127-3p/FJX1 axis." (PMID 35280790, 2022). "Although both genes have not been extensively studied in melanoma so far, MAP3K2 participates in regulation of several pathways such as MAPK signaling, β-catenin pathway and Hedgehog (Hh) pathway in medulloblastoma and osteoblasts, and FJX1 promotes angiogenesis in colorectal carcinoma." (PMID 34638331, 2021).
colon adenocarcinoma (2 papers, 2022 to 2023). "The high expression of FJX1 has negative effects on the overall survival of colon adenocarcinoma and ovarian tumor patients." (PMID 36825005, 2023).
colorectal tumor (2 papers, 2013 to 2022). "FJX1 mRNA and protein are upregulated in human colorectal tumor epithelium as compared with normal epithelium and colorectal adenomas, and high expression of FJX1 is associated with poor patient prognosis." (PMID 23922772, 2013). "FJX1 mRNA and protein are upregulated in human colorectal tumor epithelium compared to rectal adenomas, and high expression of FJX1 is linked to a poor patient prognosis, in line with our observations." (PMID 35928453, 2022). "FJX1 is a gene on chromosome 11 (11p13) and the expression of FJX1 mRNA and protein are upregulated in colorectal tumor tissues compared to normal intestinal epithelial tissues." (PMID 35928453, 2022).
cyst (2 papers, 2019 to 2024). A sac-like closed membranous structure that may be empty or contain fluid or amorphous material. "In our study, we observed separation between cyst formation and fibrotic response when Fjx1 is inactivated." (PMID 31038742, 2019). "We found that mice that are double KO for Fjx1 and Pkd1 display cyst formation comparable to that of single Pkd1 KO mice but survive longer." (PMID 31038742, 2019). "In conclusion, we show that cyst progression and fibrosis in Pkd1/Fjx1 double KO mice are partially uncoupled and demonstrate a new, yet undefined, role of Fjx1 in fibrosis, ultimately resulting in longer survival." (PMID 31038742, 2019). "In our study, Fjx1 showed aberrant expression during both the injury‐repair phase and cyst progression in Pkd1 KO mice compared with WT mice." (PMID 31038742, 2019). "However, deleting the target of Fjx1, Fat4, leads to loss of PCP in the inner ear, cochlea and the neural tube, and mild cyst formation in mouse kidney." (PMID 31038742, 2019). "Therefore, we hypothesised a role for Fjx1 in injury/repair and cyst formation." (PMID 31038742, 2019). "On the other hand, Stat3 activation, known to be involved in cyst growth 27, was not significantly different between the two genotypes, supporting the idea that Fjx1 role is related to the inflammatory/fibrotic response and not to cyst formation." (PMID 31038742, 2019). "Together with the results observed during the cyst‐induced chronic injury, these data suggest that the lack of Fjx1 leads to a reduced sensitivity to DCVC‐induced injury." (PMID 31038742, 2019). "Consistently, it was shown that simultaneous knockout of Fjx1 decelerates renal fibrosis, alleviates renal inflammation, and preserves renal function in mice with Pkd1 deletion; however, Fjx1 knockout did not markedly inhibit cyst formation." (PMID 38671465, 2024). "Thus, our data suggest that Fjx1 is not directly involved in cyst formation and that prolonged survival of the double KO mice cannot be explained by delayed cyst formation." (PMID 31038742, 2019).
head and neck cancer (2 papers, 2015 to 2019). A primary or metastatic malignant neoplasm affecting the head and neck. "Overexpression of FJX1 in the transcriptomic level was also observed in RNA-Seq data from 43 head and neck cancers compared to matched normal samples from the TCGA database." (PMID 31236144, 2019). "Taken together, these independent datasets demonstrate that FJX1 is consistently upregulated in cancers, particularly in head and neck cancer, underscoring the rationale of studying the function of this gene in these cancers." (PMID 31236144, 2019). "FJX1 is also found to be overexpressed in microarray datasets and TCGA datasets of other cancers including head and neck cancer, colorectal, and ovarian cancer." (PMID 31236144, 2019). "Notably, RNA-Seq data from 43 head and neck cancers with matched normals from the TCGA database consistently showed that tumour samples had a 2-fold elevated level of FJX1 when compared to the matched normals (p < 0.01)." (PMID 31236144, 2019). "An in vitro study on the development of immunotherapy using peptides derived from FJX1 as a treatment for head and neck cancer including NPC has shown the ability of these peptides to elicit patients' T cell cytotoxic response towards tumour cells expressing FJX1." (PMID 31236144, 2019). "Fj regulates the phosphorylation state of the cadherin repeats of Fat and Ds affecting their ability to interact with one another which could explain why upregulation of FJX1 results in increase invasion in head and neck cancer cells." (PMID 31236144, 2019). "Here, we demonstrate that all peptides were immunogenic and are able to induce anti-tumor immune responses against FJX1-expressing head and neck cancer cells, suggesting that FJX1 specific peptides could be efficacious and a viable therapy for the treatment of head and neck cancers including NPC." (PMID 26536470, 2015). "While much remains unknown about the function of FJX1, emerging studies have identified FJX1 to be amplified or overexpressed in several types of cancers including breast, lung, ovarian, colorectal, and head and neck cancers, suggesting that it could be a genetic driver for cancer." (PMID 31236144, 2019). "Notably, the human FJX1 chromosomal region, is reported to be amplified and overexpressed in oral cancer tissues and cell lines, suggesting that the protein may be a viable tumor antigen for head and neck cancers including oral cancer and NPC." (PMID 26536470, 2015).
head and neck squamous cell carcinoma (2 papers, 2022 to 2023). A squamous cell carcinoma that arises from any of the following anatomic sites: lip and oral cavity, nasal cavity, paranasal sinuses, pharynx, larynx, and salivary glands. "The overexpression of FJX1 proteins is observed in both primary and recurrent head and neck squamous cell carcinoma (HNSCC) patients." (PMID 36825005, 2023). "Interestingly, it is feasible that a dual-antigenic peptide vaccine (PV1) comprises both MAGED4B and FJX1 peptides against head and neck squamous cell carcinoma, which is now under investigation in human safety." (PMID 36825005, 2023).
oral cancer (2 papers, 2015 to 2019). "Further, FJX1 amplification was also detected in 16/16 oral cancer cell lines derived from oral squamous cell carcinoma when compared to normal keratinocytes." (PMID 31236144, 2019). "On-going studies in our laboratory have shown that large fraction of our oral cancer cell line panel including ORL195 express high levels of FJX1 protein." (PMID 26536470, 2015).
acute myeloid leukemia (1 paper, 2023). Acute myeloid leukemia (AML) is a group of neoplasms arising from precursor cells committed to the myeloid cell-line differentiation. "On the contrary, the FJX1 expression in cancer tissues was lower significantly, compared with normal tissues, including the kidney chromophobe (KICH), acute myeloid leukemia (LAML), lung adenocarcinoma (LUAD), prostate adenocarcinoma (PRAD), and skin cutaneous melanoma (SKCM)." (PMID 37324001, 2023).